TRIM24 (tripartite motif containing 24)
Description:
Transcriptional coactivator that interacts with numerous nuclear receptors and coactivators and modulates the transcription of target genes. Interacts with chromatin depending on histone H3 modifications, having the highest affinity for histone H3 that is both unmodified at 'Lys-4' (H3K4me0) and acetylated at 'Lys-23' (H3K23ac). Has E3 protein-ubiquitin ligase activity. Early in response to DNA damage, ATM kinase phosphorylates TRIM24 leading to its ubiquitination and degradation. Up-regulates ligand-dependent transcription activation by AR, GCR/NR3C1, thyroid hormone receptor (TR) and ESR1. Modulates transcription activation by retinoic acid (RA) receptors, including RARA. Plays a role in regulating retinoic acid-dependent proliferation of hepatocytes (By similarity). Also participates in innate immunity by mediating the specific 'Lys-63'-linked ubiquitination of TRAF3 leading to activation of downstream signal transduction of the type I IFN pathway. Additionally, negatively regulates NLRP3/CASP1/IL-1beta-mediated pyroptosis and cell migration probably by ubiquitinating NLRP3.
Synonyms: RNF82; TIF1; TIF1A; hTIF1; PTC6; TF1A; TIF1ALPHA
Tractability: Small molecule: a structure with a bound ligand is known; a high-quality ligand is known; it has a binding pocket of medium quality. PROTAC: it is named in the literature on targeted protein degradation; UniProt records ubiquitination sites on it; ubiquitination databases record sites on it; its protein half-life has been measured; a small molecule that binds it is known.
Target class: Epigenetic regulator; Bromodomain; Reader
Chemical probes: PMID25974391C34 (high quality), dTRIM24 (high quality)
Gene: Protein-coding gene on chromosome 7 (138,460,210 to 138,589,996, forward strand). Ensembl gene ENSG00000122779.
Subcellular location: Nucleus; Cytoplasm; Mitochondrion
Subcellular location (Human Protein Atlas): Nucleoplasm
Pathways (Reactome):
Disease: Signaling by BRAF and RAF1 fusions; Signaling by FGFR1 in disease; Signaling by cytosolic FGFR1 fusion mutants
Gene Ontology:
Molecular function: chromatin binding; estrogen response element binding; histone H3K23ac reader activity; protein binding; transcription coactivator activity; ubiquitin protein ligase activity; zinc ion binding; signaling receptor binding; nuclear receptor binding; protein kinase activity; sequence-specific DNA binding; ubiquitin-protein transferase activity
Biological process: cellular response to estrogen stimulus; protein catabolic process; protein ubiquitination; regulation of apoptotic process; regulation of protein stability; transcription by RNA polymerase II; chromatin organization; positive regulation of DNA-templated transcription; response to peptide hormone
Cellular component: cytoplasm; mitochondrion; nucleoplasm; nucleus; chromatin; cytosol; euchromatin; nuclear lumen; perichromatin fibrils
Genetic constraint (gnomAD): Loss-of-function variants: 20 observed, 97.74 expected, observed/expected ratio (o/e) 0.2, 90% interval 0.14 to 0.3. The upper end of that interval is the gene's LOEUF score, 0.3, which puts it in group 1 of 6, group 1 being the genes least tolerant of losing a copy. Missense variants: 839 observed, 1,125.2 expected, observed/expected ratio (o/e) 0.75, 90% interval 0.7 to 0.79. Synonymous variants: 407 observed, 398.91 expected, observed/expected ratio (o/e) 1.02, 90% interval 0.94 to 1.11.
Homologues: Orthologues: chimpanzee TRIM24 (100% identical), macaque TRIM24 (99% identical), pig TRIM24 (97% identical), dog TRIM24 (94% identical), mouse Trim24 (94% identical), rat Trim24 (94% identical), guinea pig TRIM24 (89% identical), rabbit TRIM24 (82% identical), tropical clawed frog trim24 (66% identical), zebrafish trim24 (37% identical). Paralogues in human: TRIM33 (49% identical), TRIM66 (27% identical), TRIM28 (23% identical), TRIM2 (13% identical), TRIM37 (13% identical), TRIM71 (13% identical), TRIM3 (12% identical), TRIM9 (12% identical), TRIM46 (12% identical), TRIM67 (11% identical), MID1 (10% identical), TRIM36 (10% identical), and 68 more.
Diseases named in the same sentence as TRIM24 in open-access papers:
TRIM24 is named in the same sentence as 118 diseases in open-access papers, as found by Europe PMC text mining. Sharing a sentence is not in itself a finding about the gene and the disease. The quoted sentences say what the papers report.
breast carcinoma (42 papers, 2012 to 2025). "Trim24 has previously been linked to cancer, showing elevated expression in several types including breast cancer, whereas gain of expression in mice leads to elevated rates of cancer." (PMID 37386214, 2023). "Meanwhile, several reports have associate the abnormal high expression of TRIM24 with the progression and poor survival of cancer such as breast cancer, gastric cancer, glioblastoma and clear cell renal cell carcinoma." (PMID 35105347, 2022). "The nuclear expression or overexpression of TRIM24 is frequently linked to a worse prognosis for patients, e.g., in breast cancer, cervical cancer, or non-small cell lung cancer (NSCLC)." (PMID 35743773, 2022). "TRIM24 has been associated with prognosis in breast cancer and over-expression of DUSP4 has been shown to improve the outcome of chemotherapy and overall survival." (PMID 33849068, 2021). "Overexpression of the TRIM24/IF-1 gene in breast cancer is associated with poor prognosis and worse survival." (PMID 25423363, 2014). "Another example illustrating the relevance of combinatorial histone modifications is the estrogen receptor co-activator TRIM24, which is overexpressed in breast cancer and associates with the specific combinatorial pattern H3K4unK23ac." (PMID 23826629, 2013). "Up-regulation of TRIM24 expression had been implicated in several human cancers such as acute promyelocytic leukaemia, papillary thyroid carcinoma and breast cancer." (PMID 22666376, 2012). "Furthermore, MCF7 breast cancer cells deficient in TRIM24 also display a reduced cell adhesion phenotype that is thought to contribute to cancer cell proliferation, migration, and metastasis." (PMID 36690785, 2023). "High expression of TRIM24 is associated with poor survival in breast cancer patients." (PMID 35105347, 2022). "Numerous evidences indicate that TRIM24 upregulation is significantly associated with cancer development and poor prognosis in multiple cancer types such as bladder cancer, gastric cancer, non-small cell lung cancer, and breast cancer." (PMID 33643926, 2021). "Even if rapid progress has been made in the development of new small-molecule tools targeting the PHD finger domains, selective inhibitors, i.e., targeting TRIM24, frequently overexpressed in breast cancer and associated with poor overall survival and tumor progression, have not yet been developed." (PMID 30634442, 2019). "It was reported that TRIM24 could activate estrogen-dependent genes associated with cellular proliferation and tumor development in breast cancer, and was negatively correlated with survival of this disease." (PMID 27689360, 2016). "It has been reported that overexpression of TRIM24 could promote prostate cancer progress, and high level of TRIM24 proteins was associated with poor prognosis in breast cancer." (PMID 24409330, 2014). "Furthermore, the aberrant expression of TRIM24 is significantly associated with poor prognosis patients with breast cancer." (PMID 23717505, 2013). "The PHD and BRD are potential therapeutic targets due to the roles of TRIM24 in breast cancer progression." (PMID 41243558, 2025). "A chromatin immunoprecipitation (ChIP)-seq based analysis unveiled a robust co-localization of the H4K5ac and H4K8ac histone signatures in proximity to transcription start sites for various hub genes or genes targeted by TRIM24 in breast cancer." (PMID 39160596, 2024).
breast carcinoma (continued). "Given that TRIM24 functions as a transcriptional co‐activator in breast cancer, prostate cancer, and GBM, we reasoned that TRIM24 activated these pathways by regulating the transcriptional activation of multiple regulators in these pathways." (PMID 38828688, 2024). "A notable example involves tripartite motif-containing protein 24 (TRIM24), a histone reader aberrantly expressed in breast cancer." (PMID 39127633, 2024). "TRIM24 is a possible prognostic marker for prostate cancer, head and neck squamous cell carcinomas and breast cancer." (PMID 36276071, 2022). "TRIM24 is claimed aberrantly activated in a number of cancers, such as breast cancer, prostate cancer and lung cancer." (PMID 35105347, 2022). "TRIM24 can also act as a synergistic activator of estrogen receptor (ER) to promote the proliferation of breast cancer cells, thereby promoting the occurrence of breast cancer." (PMID 35105347, 2022). "We found that TRIM24 is a co-regulator of estrogen receptor (ER)-regulated genes in breast cancer-derived MCF7 cells." (PMID 34508101, 2021). "TRIM24 is known to be highly overexpressed in several cancers including non-small cell lung cancer, breast cancer, cervical cancer, hepatocellular carcinoma, as well as prostate and gastric cancers." (PMID 34298819, 2021). "The C-terminal domains of PHD and BROMO in TRIM24 can bind to chromatin and serve as potential therapeutic targets for breast cancer." (PMID 34943167, 2021). "High levels of TRIM24, determined by tumor immunohistochemistry (IHC), correlate with poor survival of breast cancer patients." (PMID 34508101, 2021). "TRIM24 activated atherogenesis and cell viability in breast cancer cell lines and S100A9 inhibited the metabolism of amino acids." (PMID 34575874, 2021). "Here, we present evidence that TRIM24 is an oncogenic histone reader with the ability to drive an aggressive breast cancer phenotype in a mouse model with pathologic and molecular features that parallel MpBC human patient data." (PMID 34508101, 2021). "In the study, the regulatory network of TRIM24 activated atherogenesis and cell viability in breast cancer cell lines." (PMID 34575874, 2021). "Here, we show that <3-fold overexpression of Trim24 in mammary epithelia is sufficient to induce mammary tumors, 67% of which are characterized as carcinosarcomas." (PMID 34508101, 2021). "An unbiased clustering analysis showed a clear distinction between gene expression profiles of MMTV-Cre-expressing, normal control mammary glands, non-TRIM24-overexpressing mammary tumors and TRIM24-overexpressing mammary tumors." (PMID 34508101, 2021). "Differential gene expression analysis identified glycolysis and EMT as the top up-regulated pathways in TRIM24-driven mammary tumors, robustly active even in end-stage tumors, analyzed here." (PMID 34508101, 2021). "TRIM24 over-expression correlates with poor survival outcomes in breast cancer patients due to its oncogenic potential in driving ER activity." (PMID 30634442, 2019). "Previous studies determined that elevated H3K23ac and TRIM24 predict shorter overall survival of breast cancer patients." (PMID 30591655, 2018). "Overexpression of the TRIM24 was found in breast cancer, non-small-cell lung cancer, and malignant glioma." (PMID 29862279, 2018). "It is overexpressed in human breast cancer and correlated with poor patient prognosis, indicating a potentially oncogenic function for TRIM24 in human cancers." (PMID 29862279, 2018). "According to recently published reports, TRIM24 was found to be correlated with poor survival and was involved in cell proliferation and metastasis in colon cancer and breast cancer." (PMID 28061796, 2017). "TRIM24 was reported as an oncogenic transcription factor in ER-driven breast cancer and AR-driven prostate cancer." (PMID 29129908, 2017).
breast carcinoma (continued). "Recent research in acute promyelocytic leukaemia, myeloproliferative syndrome, papillary thyroid carcinoma, breast cancer, and non-small cell lung cancer has shown that the expression of TRIM24 was up-regulated." (PMID 24409330, 2014). "Upon estrogen treatment of MCF7 breast cancer cells, Trim24 is recruited along with ERα to estrogen responsive genes that are also became enriched in acetyl-H3K23." (PMID 22808194, 2012). "Previous research concerning its expression pattern showed that TRIM24 was overexpressed in breast cancers at both mRNA and protein levels and its overexpression was correlated with ER, PR status and poor prognosis." (PMID 22666376, 2012). "Aberrant expression of TRIM24, which is increased in human breast cancer, negatively correlates with patient survival and may serve as a new prognostic marker." (PMID 39160596, 2024). "Notably, TRIM24 acts as a synergistic activator of the estrogen receptor, promoting breast cancer cell proliferation and contributing to the occurrence of breast cancer." (PMID 39160596, 2024). "This study highlights the significant role of TRIM24 and H3K23ac in breast cancer, suggesting that TRIM24 small-molecule inhibitors could benefit estrogen receptor- and progesterone receptor-negative or HER2-positive patients." (PMID 39160596, 2024). "In a study using a mouse model, the conditional overexpression of TRIM24 in mouse mammary epithelia leads to the spontaneous development of mammary tumors, with TRIM24 exerting its impact through its function as a histone reader in chromatin association and the disruption of EMT process." (PMID 39160596, 2024). "However, TRIM24 can not only be found in the nuclei but also in the cytoplasm of tumor cells, e.g., in prostate cancer and breast cancer." (PMID 35743773, 2022). "Overexpression of TRIM24 negatively correlates with survival of breast cancer patients." (PMID 35803934, 2022). "Importantly, we observed a TRIM24 signature in a rare and aggressive form of human breast cancer, MpBC." (PMID 34508101, 2021). "The selective inhibitor IACS-9571 has dual specificity towards the BRPF1 and TRIM24 bromodomains and may be therapeutically useful for acute myeloid leukemia or breast cancer patients." (PMID 34298819, 2021). "Given the functional studies in cellulo and correlative links between TRIM24 and human cancers, we hypothesized that TRIM24 is a potent oncogene that reprograms transcriptional networks and promotes development of aggressive breast cancers." (PMID 34508101, 2021). "Thus, a mouse model of human MpBC, driven by histone reader TRIM24, was used to nominate PI3K/mTOR inhibitors and a TRIM24-specific PROTAC for further assessment as potential therapeutic approaches for a rare subclass of chemorefractory breast cancer patients." (PMID 34508101, 2021). "Given the established role of TRIM24 protein as a transcriptional co-activator in breast cancer and prostate cancer, we hypothesized that TRIM24 functions as a transcriptional co-activator in gliomas." (PMID 29129908, 2017).
breast carcinoma (continued). "Elevated expression of TRIM24 could promote progression of prostate cancer and negatively correlated with survival of breast cancer patients." (PMID 22666376, 2012). "Using array CGH analysis, gains at the TRIM24 locus (7p34) were detected in approximately 10% of the breast cancers suggesting that genomic alterations may partly account for the TRIM24 overexpression in breast cancer." (PMID 23717505, 2013). "Moreover, TRIM24 overexpression correlated with survival of breast cancer patients." (PMID 22666376, 2012). "We and others have previously shown that epigenetic coregulators such as ZMYND8, CHD4, CARM1, TRIM24, and JMJD2C are frequently amplified or upregulated to promote breast cancer progression through their role in epigenetic reprogramming." (PMID 37655663, 2023). "KAT6A promotes SMAD3 binding to oncogenic chromatin modifier TRIM24 and disrupts its interaction with the tumor suppressor TRIM33, which lead to the tumor cell metastasis in breast cancer." (PMID 35430805, 2022). "The regulatory network TRIM24 was involved in showed that TRIM24, YAP1, Ifn, Ifnar, SOCS1, and S100A8 together activated atherogenesis and cell viability of breast cancer cell lines through 18 genes, including AKT1, ID2, etc.." (PMID 34575874, 2021). "TRIM24 also interacts with HDAC1 to suppress HCC and interacts with other histone marks such as H3K9ac, H3K14ac, H3K27ac and H4ac in breast cancer." (PMID 32731534, 2020). "Upon DNA damage, ATM phosphorylates TRIM24 at Ser768, promoting autoubiquitination of TRIM24 and its subsequent degradation in the MCF7 breast cancer cell line." (PMID 32731534, 2020). "TRIM24 and TRIM33 bind to each other in breast cancer cells, but this interaction remains unchanged in response to the DNA intercalating agent adriamycin or 10 Gy irradiation." (PMID 32731534, 2020). "Interestingly, both TRIM24 and H3K23ac levels are higher in human epidermal growth factor receptor 2 (HER2)-positive breast cancer patients, positively correlating with HER2 levels." (PMID 39160596, 2024). "Other approaches involve delivery of compounds such as oridonin (in breast cancer), suppressing NRF2 and increasing apoptosis, or modifications of C19-position substituted geldanamycin directed to NRF2 for esophageal squamous cancer, or finally, direct inhibition of antioxidant systems or of TRIM24." (PMID 40676628, 2025). "In addition, overexpression of TRIM24 is correlated with survival of breast cancer patients and with pTNM stage and differentiation in non-small cell lung cancer." (PMID 24409330, 2014).